MDM2 (MDM2 proto-oncogene)
Diseases named in the same sentence as MDM2 in open-access papers (continued):
Sharing a sentence is not in itself a finding about the gene and the disease.
melanoma (continued). "Consequently, in MAPKi-resistant melanoma cells, nuclear enrichment of MDM2 most probably resulted in downregulation of FBXW7 and subsequent upregulation of p63." (PMID 36613518, 2022). "For instance, MDM2 overexpression in melanoma is a prognostic marker, which is associated with better clinical outcome, thus the cleavage of MDM2 is unlikely to promote tumor suppression there." (PMID 35444189, 2022). "USP15 stabilizes MDM2 and induces the apoptosis of melanoma and colon cancer cells." (PMID 36163170, 2022). "In addition to FBXW7 self-ubiquitination, studies have shown that in melanoma cells the nuclear accumulation of MDM2 leads to MDM2-dependent ubiquitination and rapid downregulation of FBXW7 resulting in upregulation of FBXW7-degraded oncoproteins such as p63." (PMID 35346215, 2022). "Recent studies of mucosal melanomas by whole exome sequencing demonstrated that mucosal melanomas have a low mutational burden, with frequent structural variants commonly affecting CDK4, MDM2 and TERT." (PMID 34571863, 2021). "We observed that MDM4 is amplified in melanomas, more so than the related protein MDM2." (PMID 34697572, 2021). "Compared to normal melanocytes, iASPP, MDM2 and cyclin B1 are often overexpressed in melanoma." (PMID 34911439, 2021). "This was probably the first case of MDM2 amplificated, hyperprogressive melanoma." (PMID 32110946, 2020). "Nuclear delivery of antibodies has been demonstrated by using a bivalent scFv derivative of cell and nuclear penetrating autoantibody 3E10 fused to an anti-MDM2 antibody, which impaired the growth of melanoma cells and melanoma xenografts sensitive to MDM2 inhibition." (PMID 30405420, 2018). "In addition, miR-661 was described as a negative regulator of mdm2 and mdm4 in several cell lines from melanoma, lung, breast, and ovarian cancer." (PMID 24616890, 2014).
melanoma (continued). "Interestingly, previous studies showed that Mdm2 and Mdm4 are highly expressed in melanoma." (PMID 39857778, 2025). "Additionally, other biomarkers such as MITF (microphthalmia-associated transcription factor), IDO (indoleamine 2,3-dioxygenase), and MDM2 (mouse double minute 2 homolog) have shown promise in regulating melanoma cell behavior, offering potential avenues for targeted therapeutic strategies." (PMID 37629523, 2023). "We also searched for additional candidate functional MDM2/MDM4 variants in high LD with our tested single nucleotide polymorphisms (SNPs) that contribute to the genetic environment and create more or less favorable conditions in skin and/or distal tissues prone to melanoma metastases." (PMID 37345045, 2023). "Notably, mounting evidence has demonstrated the oncogenic role of MDM2 in melanoma." (PMID 35468881, 2022). "On that note, we have previously examined the response of seven human melanoma cell lines and five melanoma patient-derived xenografts to treatment with a CDK4/6 inhibitor alone or in combination with an MDM2 inhibitor." (PMID 40904502, 2025). "In some studies, synchronous inhibition of MDM2 and BRAF is more effective than BRAF monotherapy in BRAFV600E-positive melanomas." (PMID 38396916, 2024). "For T cells it was shown that MDM2 inhibition can induce production of tumour necrosis factor α and IFN-γ, whereas in melanoma cells MDM2 inhibition induces interleukin-15 (IL-15) production." (PMID 39530091, 2024). "In this study, we observed the presence of MDM2 and SURVIVIN expression in in-transit metastases of melanoma and the correlation between this and the clinical response to ILP with TNF and melphalan." (PMID 38138884, 2023). "Elevated levels of MDM2 and MDMX proteins have been observed in certain cancers such as melanoma, Ewing’s sarcoma, and colon carcinoma." (PMID 37509256, 2023). "Because MDM2 overexpression is an independent predictor of survival in patients with melanoma, it is possible that GSK-3 regulates NUMB expression in an MDM2-dependent manner." (PMID 34883044, 2022). "Although melanoma cells are highly resistant to MAPK inhibitors, a combination with MDM2 inhibitor, Nutlin-3A, resulted in elevated FBXW7 expression, p63 degradation, and apoptosis of melanoma cells effectively reversing MAPK inhibitor resistance." (PMID 35346215, 2022).
melanoma (continued). "In melanoma, the combination of AURKA inhibitors and MDM2 inhibitors synergistically promoted anti-tumor immune cell infiltration in immunocompetent mice." (PMID 35205315, 2022). "A microarray analysis of the syngeneic murine melanoma model B16F10 upon a dual treatment of carbon-ion external radiotherapy and 131I-Benzamide showed an enrichment of the genes PARP3, MDM2, GADD45A, which were also found to be upregulated in our study." (PMID 34830750, 2021). "miR-579-3p also controls melanoma progression and its sensitivity to target therapy by targeting the 3′UTR of two oncoproteins: BRAF and an E3 ubiquitin protein ligase, MDM2." (PMID 34288804, 2021). "One study showed that AURKA and MDM2 antagonism with MLN8237 and Nutlin-3 halted melanoma growth by inducing growth arrest and senescence, limiting the lifespans of senescent cells, and enhancing tumor immune infiltration and clearance." (PMID 33451333, 2021). "Remarkably, both of MDM2 and MDMX have been shown to be therapeutic target candidates for anti-melanoma therapies." (PMID 32686661, 2020). "We therefore investigated the response of metastatic acral and mucosal melanoma to ICI in regard to MDM2/4 or EGFR amplifications and melanoma type." (PMID 32110946, 2020). "The aim of this study was to check possible correlations between hyperprogression to checkpoint inhibitors and amplification (≥4 copies) of MDM2, MDM4 or EGFR in acral and mucosal melanoma." (PMID 32110946, 2020). "We investigated the combination with trametinib, a clinically approved compound, and MDM2 inhibitors, nutlin-3/RG7388/HDM201 (the latter two are in clinical trials) in melanoma cell lines, which has direct translational implications to the clinical setting." (PMID 30577494, 2018).
melanoma (continued). "Comparison of genes amplified in our samples with published gene lists from two large melanoma studies while revealing very little overlap did identify BRAF, MDM2, and NRAS, genes known to be important in melanoma." (PMID 21494657, 2011). "This study revealed that targeting MDM2 in combination with CDK4/6 inhibitors could enhance the therapeutic efficacy and overcome resistance in melanoma cells." (PMID 39200315, 2024). "During our experimentation with MLN4924, we found that inhibition of the NEDD8 pathway in A375 melanoma cells dramatically decreases the protein levels of Mdmx, but not of Mdm2." (PMID 39404389, 2024). "In the analyzed melanomas, we found seven tumors positive for both pRSK and MDM2 (100% match); two tumors were negative for both pRSK and MDM2 staining (100% match)." (PMID 39329730, 2024). "In this study, we investigated the correlation between the tumor gene expression levels of two key regulators of apoptosis—SURVIVIN and MDM2—and the tumor response or clinical outcomes in patients treated with ILP for in-transit melanoma metastases of the limbs." (PMID 38138884, 2023). "The hypothesis was that MDM2 and SURVIVIN may be involved in the chemoresistance mechanisms of TNF melanoma metastases, interfering with its cytotoxic effect and, in particular, direct toxicity mediated by apoptosis." (PMID 38138884, 2023). "Tumor MDM2 gene expression appears to correlate with clinical response and local disease-free survival in patients undergoing limb ILP with TNF and melphalan for in-transit melanoma metastases." (PMID 38138884, 2023). "Translation of the synergy between the Siremadlin (MDM2 inhibitor) and Trametinib (MEK inhibitor) combination observed in vitro into in vivo synergistic efficacy in melanoma requires estimation of the interaction between these molecules at the pharmacokinetic (PK) and pharmacodynamic (PD) levels." (PMID 36361773, 2022). "Additionally, oncogenes that can be regulated by epigenetic modifiers and support melanoma progression and development include RAS, ERK, c-jun, MITF, MDM2, and BCL-2." (PMID 34944799, 2021). "Furthermore, MDM2 relies on the regulation of transcription factor E2F1 to promote the invasion and motility of melanoma cells." (PMID 32964032, 2020). "Only three melanomas were positive for an increase in pRSK but negative for MDM2 (25% of total)." (PMID 39329730, 2024).
melanoma (continued). "Further analysis revealed that MDM2 inhibitors promoted the frequency of CD8+ CD73+ TCF-1+ IFN-γ+ TNF+ T cells and T-cell receptor activation and that isolation of these T cells from mice and transfer to PD-1-treated mice increased survival and activated immune memory against melanoma cells." (PMID 39263534, 2024). "Our approach supports the role of AKT1 and MDM2 protein signatures as drivers of EMT in melanoma cancer and suggests that MDM2 plus AKT1 inhibitors could be a promising combination for a novel anti-metastatic regimen in high E2F1-expressing melanoma patients." (PMID 37993971, 2023). "However, the MDM2 protein is frequently upregulated (or activated) in melanoma secondary to the decreased or absent expression of MDM2 inhibitors, such as p14ARF." (PMID 35635631, 2022). "MDM2 amplification and overexpression are found at a high frequency in soft tissue tumours, e.g., liposarcoma, at a lower frequency in glioblastoma and breast cancer, but not in tumour types like leukaemia, lymphoma, and melanoma." (PMID 34711913, 2021). "Moreover, as MDM2 inhibitors are already available for clinical use, we propose to test them in a clinical trial to assess whether or not their administration would improve the results of TNF-based ILP in patients with in-transit melanoma metastasis." (PMID 38138884, 2023). "WGS studies have suggested that TWT melanomas, commonly of the AM subtype, are more likely to have focal amplifications of CCND1, MDM2, KIT, and KRAS, as well as CDK4 and CDK6, than non-TWT melanomas." (PMID 39858514, 2025). "Lastly, it is worth noting that MDM2 or CDK4 amplification is not exclusive to mesenchymal neoplasms; this genetic alteration has also been observed in other epithelial neoplasms or melanomas." (PMID 38275873, 2024). "In line with this, we found gene amplifications of MDM2 and MDM4 in 26% and of CDK4/6 in 13% of the melanoma biopsies of patients that did not respond to ICB." (PMID 32165639, 2020). "Furthermore, besides SF3B1 and KIT mutations, other variants have been described in the context of mucosal melanoma, including amplifications of CCND1, MDM2 and KRAS, however this was not assessed this cohort and could represent a source of additional driver eventsin this cohort." (PMID 30847022, 2019).